SKOR1 (SKI family transcriptional corepressor 1)
Description:
Acts as a transcriptional corepressor of LBX1 (By similarity). Inhibits BMP signaling.
Synonyms: CORL1; FUSSEL15; LBXCOR1
Tractability: No criterion of Open Targets' tractability assessment is met for any kind of drug.
Gene: Protein-coding gene on chromosome 15 (67,819,704 to 67,834,582, forward strand). Ensembl gene ENSG00000188779.
Subcellular location: Nucleus
Subcellular location (Human Protein Atlas): Nucleoplasm
Gene Ontology:
Molecular function: sequence-specific double-stranded DNA binding; SMAD binding; DNA-binding transcription factor activity, RNA polymerase II-specific; RNA polymerase II cis-regulatory region sequence-specific DNA binding
Biological process: negative regulation of BMP signaling pathway; negative regulation of transcription by RNA polymerase II; regulation of DNA-templated transcription; negative regulation of transmembrane receptor protein serine/threonine kinase signaling pathway
Cellular component: dendrite; neuronal cell body; cytoplasm; nucleus; transcription regulator complex
Genetic constraint (gnomAD): Loss-of-function variants: 38 observed, 61.88 expected, observed/expected ratio (o/e) 0.61, 90% interval 0.47 to 0.81. The upper end of that interval is the gene's LOEUF score, 0.81, which puts it in group 3 of 6, group 1 being the genes least tolerant of losing a copy. Missense variants: 1,288 observed, 1,188.9 expected, observed/expected ratio (o/e) 1.08, 90% interval 1.03 to 1.13. Synonymous variants: 623 observed, 531.38 expected, observed/expected ratio (o/e) 1.17, 90% interval 1.1 to 1.25.
Homologues: Orthologues: chimpanzee SKOR1 (99% identical), macaque SKOR1 (98% identical), mouse Skor1 (93% identical), dog SKOR1 (92% identical), guinea pig SKOR1 (91% identical), pig SKOR1 (91% identical), rat Skor1 (90% identical), zebrafish skor1a (49% identical), tropical clawed frog skor1 (49% identical), zebrafish skor1b (46% identical). Paralogues in human: SKOR2 (42% identical), SKI (18% identical), SKIL (13% identical).
Diseases named in the same sentence as SKOR1 in open-access papers:
SKOR1 is named in the same sentence as 10 diseases in open-access papers, as found by Europe PMC text mining. Sharing a sentence is not in itself a finding about the gene and the disease. The quoted sentences say what the papers report.
restless legs syndrome (5 papers, 2017 to 2023). A condition that occurs while resting or lying in bed; it is characterized by an irresistible urgency to move the legs to obtain relief from a strange and uncomfortable sensation in the legs. "Mouse Skor1 is expressed in dI4 and dI5 spinal interneurons, where it binds Lbx1, and human Skor1 has been implicated in Restless legs syndrome (also known as Willis-Ekbom disease)." (PMID 38017520, 2023). "Among others Skor1 and Skor2 are involved in the development of Purkinje neurons and a mutation of Skor1 has been found to be associated with restless legs syndrome." (PMID 35030229, 2022). "Pathophysiologically, Skor1 has mainly been linked to restless leg syndrome and localized scleroderma." (PMID 35030229, 2022). "SKOR1 has been widely reported to play a transcriptional regulatory role on genes related to restless legs syndrome, but is new to T2D." (PMID 34848693, 2021).
Obesity (3 papers, 2015 to 2025). Accumulation of substantial excess body fat. "Transcripts for several candidate genes for obesity were absent in the whole brain or absent in specific regions of the brain (Cyp17a1, Gdf15, Gpr151, Lmx1b, Olig3, Sbk1, Sim1, Skor1, Tnni3k)." (PMID 39920851, 2025).
Alzheimer disease (1 paper, 2017). A progressive, neurodegenerative disease characterized by loss of function and death of nerve cells in several areas of the brain leading to loss of cognitive function such as memory and language. "The risk locus on chromosome 15q23 (encompassing MAP2K5 and SKOR1) overlaps with GWAS signals of four different traits, including the posterior cortical atrophy variant of Alzheimer's disease (appendix pp 39–41)." (PMID 29029846, 2017).
Insulin resistance (1 paper, 2021). Increased resistance towards insulin, that is, diminished effectiveness of insulin in reducing blood glucose levels. "Mechanism research reveals that NK-derived exosomal miR-1249-3p relieves insulin resistance and inflammation by targeting SKOR1, which interacts with SMAD6 and promotes glucose homeostasis by suppressing the TLR4/NF-κB signaling pathway." (PMID 34848693, 2021). "Similarly, overexpression of SKOR1 induced insulin resistance and inflammation in 3T3-L1 adipocytes and AML12 cells, which was neutralized by the miR-1249-3p mimic." (PMID 34848693, 2021).
tumor (2 papers, 2011 to 2024). "Taken together, these results demonstrate that the overexpression of PDSS2-Del2 in HCC cells enhances MST1 secretion by expediting SKOR1 degradation, subsequently recruiting macrophages into the tumor microenvironment." (PMID 39695147, 2024).
cancer (1 paper, 2022). A tumor composed of atypical neoplastic, often pleomorphic cells that invade other tissues. "But neither Skor1 nor Skor2 have been reported to be involved in cancer progression." (PMID 35030229, 2022).
SKOR1 also shares sentences with these, for which no sentence is quoted: Ataxia (1 paper); colorectal cancer (1); movement disorder (1); posterior cortical atrophy (1).